FGF19 (fibroblast growth factor 19)
Diseases named in the same sentence as FGF19 in open-access papers (continued):
Sharing a sentence is not in itself a finding about the gene and the disease.
type 2 diabetes (continued). "The enterohepatic pathway involving the fibroblast growth factor 19 (FGF19) and bile acids (BA) has been linked with the etiology and remission of type 2 diabetes (T2D) following Roux-en-Y gastric bypass (RYGB) surgery." (PMID 24465600, 2014). "In our study, the levels of FGF-2, FGF-19, FGF-22, and FGF-23 were measured in patients with type 1 and type 2 diabetes and compared with healthy controls." (PMID 40943671, 2025). "The study observed a significant relationship between the levels of FGF19 and FGF22 in the serum of patients with type 1 and type 2 diabetes, as well as in the control group (p < 0.001; p < 0.001)." (PMID 40943671, 2025). "The study aimed to analyze and compare the concentrations of selected fibroblast growth factors, FGF-2, FGF-19, FGF-22, and FGF-23, in the plasma of patients with type 1 and type 2 diabetes with those of the control group." (PMID 40943671, 2025). "The study observed a difference in the relationship between the median serum concentrations of FGF19 and FGF22 in patients with type 1 and type 2 diabetes, as well as in the control group (p < 0.001; p < 0.001)." (PMID 40943671, 2025). "Decreased circulating FGF19 levels have been reported in women with GDM, and in subjects with type 2 diabetes." (PMID 35145481, 2021). "Overall, these results indicate that both age and BMI are consistently associated with reduced concentrations of FGF-19 and FGF-22, particularly in patients with type 2 diabetes, whereas FGF-2 and FGF-23 showed no consistent correlations with either parameter." (PMID 40943671, 2025). "The findings of this study suggest that fibroblast growth factors, specifically FGF-19 and FGF-22, may play crucial roles in the pathophysiology of both type 1 and type 2 diabetes." (PMID 40943671, 2025). "The aim of the present study was to investigate whether serum FGF19 levels were related to the arteriosclerosis parameters, including baPWV and AIP, in patients with type 2 diabetes." (PMID 32477430, 2020). "FGF19 values tended to be lower in type 2 diabetes patients compared with controls, but were not statistically significant." (PMID 29866129, 2018). "Fibroblast growth factor 19 (FGF19) takes part in maintaining the balance of glycolipids and may be involved in regulating the secretory activity of islet beta cells in patients with type 2 diabetes." (PMID 31572498, 2019). "The intraventricular injection of FGF19 can increase phosphorylated AKT levels in the liver, quadriceps, and white adipose tissue, suggesting that FGF19 can enhance insulin sensitivity, indicating that it may represent a potential drug for the treatment of type 2 diabetes." (PMID 34307371, 2021). "In a phase 2 randomized controlled trial in patients with type 2 diabetes, aldafermin (NGM282), an engineered FGF19 analog, did not reduce plasma glucose or HbA1c, although modest weight reduction was observed at higher dose." (PMID 41522208, 2026). "In the present study, we aimed to explore whether serum FGF19 levels were related to arteriosclerosis parameters, including arterial stiffness and atherogenic index of plasma (AIP), in patients with type 2 diabetes (T2D)." (PMID 32477430, 2020). "Ultimately, the authors demonstrated a negative relationship between FGF19 and AIP (r = –0.312, P = 0.05) that existed in MS patients with type 2 diabetes." (PMID 23940810, 2013).
liver cancer (29 papers, 2013 to 2026). An epithelial or non-epithelial malignant neoplasm that arises from the liver. "Previous studies have shown that the expression of FGF19 is significantly higher in patients with liver cirrhosis and liver cancer and is significantly associated with the pathologic stage of liver cancer." (PMID 32104677, 2020). "FGF19 expression was positively associated with a larger tumor size, more advanced Barcelona Clinic Liver Cancer (BCLC) stage, early recurrence, and poor prognosis." (PMID 32154250, 2020). "In experimental models, liver cancer development is greatly accelerated by the combined overexpression of FGF19 and MYC, resulting in more aggressive tumor phenotypes." (PMID 41328353, 2026). "FGFR4 targeting agents are an area of high interest in liver cancer, where a subset of patients exhibits an amplification of FGF19, a unique FGFR4 ligand." (PMID 40731412, 2025). "Components of the FGF19 subfamily act as endocrine hormones, of which FGF19 is the main representative involved in liver cancer." (PMID 38473265, 2024). "Activation of FXR in turn induces liver cancer through overexpression of fibroblast growth factor 19 (FGF19)." (PMID 35178126, 2022). "In liver cancer, ER stress enhanced the transcriptional activation of FGF19 mediated by ATF4, and antiapoptotic ability was observed to increase during ER stress." (PMID 33981224, 2021). "FGF19 and its receptor FGFR4 are oncogenic drivers of liver cancer and associated with a poor prognosis." (PMID 33809909, 2021). "Among the 5 liver cancer cell lines used in this study, 3 cell lines have oncogenic alterations known to activate the RAS/MAPK pathway (Huh7 and SNU387 with FGF19 amplifications; HepG2 with NRAS mutation)." (PMID 34458148, 2021). "U3-1784, a novel FGFR4 targeting antibody, exerts strong antitumor effects specific to liver cancer cells overexpressing FGF19." (PMID 34576070, 2021). "Focal amplification on 5p15.33 (TERT) and 11q13.3 (CCND1, FGF19) was found in 7 (38.1%) and 3 (9.52%) liver cancer patients, respectively." (PMID 32458568, 2020). "For example, liver cancers with both FGF19 amplification/overexpression and expression of β-klotho were sensitive to FGFR kinase inhibition." (PMID 28008155, 2017). "FGF19 mRNA levels correlated with gene copy numbers in human liver cancer, as well as in other cancer types." (PMID 28508871, 2017). "Overexpression of FGF19/FGFR4 significantly correlated with EpCAM as a marker of hepatic cancer stem cells within the fatty-steatosis-cirrhosis-HCC sequence." (PMID 27447573, 2016). "FGF19 gene amplification has been reported in 7.8% of liver cancers in the TCGA database (cBioPortal database), consistent with the frequency observed in the present study." (PMID 27384874, 2016). "The frequency of FGF19 amplification in a TCGA liver cancer dataset (15/193, 7.8%) was consistent with the data obtained from the 35 non-responders." (PMID 27384874, 2016). "Several genes previously implicated in liver cancer were discovered by our screening, including KLB, FGF19, FNDC3 and CCND1." (PMID 23776502, 2013). "The mechanism of this synergistic effect remains unclear and requires further research to elucidate the potential of treating liver cancer through FGF19 and MYC." (PMID 41328353, 2026). "Since CCND1 and FGF19 are both equally significant driver genes of the 11q13.3 amplicon in liver cancer, 11q13.3 amplification may serve as a useful biomarker for individuals who are expected to respond favorably to anti-FGF19 treatment." (PMID 38021627, 2023). "The drugs FGF401 and vinorelbine, when working together synergistically, could be effective in treating those liver cancers driven by the activity of the fibroblast growth factor 19 (FGF19) protein." (PMID 33235319, 2020).
liver cancer (continued). "Similarly to CRC, the overexpression of FGF19 leads to the overactivation of FGFR4 in liver cancer." (PMID 39796710, 2024). "Fibroblast growth factor 19 (FGF19) which located on chr11q13.3 locus, facilitated the self-renewal of liver cancer stem cells." (PMID 37007126, 2023). "An animal model showed that a neutralizing antibody against FGF19 was able to abrogate liver cancer development in transgenic mice and inhibited xenograft tumors from HCC and colon cancer, suggesting feasibility of FGF19 as a therapeutic target." (PMID 32154250, 2020). "Overexpression of FGF19 in mice results in liver cancers that are sensitive to anti-FGFR-4 and anti-FGF19 antibodies." (PMID 33235319, 2020). "Similarly, in the FGF19 transgenic mouse model, LD1 significantly reduces liver weight, effectively preventing the development of liver cancer." (PMID 41328353, 2026). "But more importantly, the pattern of increasing expression of FGF19, FGFR4 and EpCAM within the HCC, suggests a mechanistic interaction between the fibroblast growth factor/receptor and hepatic cancer stem cells, which has not been described prior to this study." (PMID 27447573, 2016).
metabolic syndrome (29 papers, 2011 to 2025). A cluster of metabolic risk factors for CARDIOVASCULAR DISEASES and TYPE 2 DIABETES MELLITUS. "The statistical significance of the observed association between HOMA-IR and FGF-19 disappeared when BMI, hypertension and dyslipidemia were added to the statistical model, suggesting a broader association with an unhealthy metabolic status." (PMID 41169463, 2025). "Previous studies have also found that FGF19 is associated with lipid metabolism in patients with metabolic syndrome and healthy controls." (PMID 36927328, 2023). "However, whether SREBP is the underlying mechanism by which FGF-19 induces dyslipidemia in patients with hypothyroidism still needs more research." (PMID 34784265, 2022). "Associations between cBAs, FGF-19, and HOMA-IR were assessed via linear regression, adjusting for age, sex, BMI, diet, alcohol intake, hypertension, and dyslipidemia." (PMID 41169463, 2025). "Through the reduction of liver fat content and plasma glucose and the improvement of the lipid formula of the blood, FGF19 protects against metabolic syndrome." (PMID 38455043, 2024). "The range of atherosclerotic lesions in the aorta of ApoE−/− mice with dyslipidemia was significantly reduced in the treatment with NGM282 (the analog of FGF19)." (PMID 32528406, 2020). "ACOX1 was found to be increased by compounds including FGF19 (Fibroblast growth factor 19, a hormonal gut-derived peptide) and nordihydroguaiaretic acid (a Creosote bush metabolite), which have been shown to improve metabolic syndrome." (PMID 29765501, 2018). "Whereas insulin was released within minutes of a meal, FGF19 serum levels peaked 2 h after a meal, and, accordingly, circulating FGF19 levels in humans inversely correlated with fasting glucose levels and metabolic syndrome." (PMID 24260557, 2013). "Understanding the effects of FGF19 and FGF21 on bone metabolism is important as FGF19 and FGF21 analogues may be used to treat disorders associated with the metabolic syndrome in future." (PMID 39341924, 2024). "Moreover, when compared to patients with T2DM, FGF19 levels were markedly reduced in T2DM patients with metabolic syndrome." (PMID 39574905, 2024). "Multiple logistic regression analysis was conducted with the diagnosis of subAS at year 3 as the dependent variable and per 1-SD increase in baseline serum FGF19 level, age, BMI, HbA1c, smoking, alcohol consumption, presence of hypertension, and presence of dyslipidemia as independent variables." (PMID 32528406, 2020). "Likewise, FGF19 serum levels peak near 2 h after a meal, and accordingly, circulating FGF19 levels in humans negatively correlate with fasting glucose levels and metabolic syndrome." (PMID 26931208, 2016). "Interestingly, serum FGF19 levels were lower in T2DM patients with metabolic syndrome and in obese patients." (PMID 24260557, 2013). "Interestingly, endocrine hormones secreted by the gallbladder, such as FGF19, may provide another possible mechanism for the development of metabolic syndrome after cholecystectomy." (PMID 34917640, 2021). "The analogs and mimetics of FGF19 and FGF21 have been repeatedly observed to improve dyslipidemia and NAFLD in multiple clinical trials." (PMID 36902015, 2023). "FGF19, like FXR agonists, has demonstrated potential to improve liver histology, but also exacerbates dyslipidemia already common in NASH patients." (PMID 33381084, 2020). "In addition, we also listed several novel identified modulatory biomarkers which play an important role in the regulation of dyslipidemia induced by hypothyroidism, including PCSK9, ANGPTL3, ANGPTL8, FGF-21, FGF-19, and several microRNAs." (PMID 34784265, 2022). "Thus, a possible increased FGF19 content in LAL-D patients could lead to a more hydrophobic BA pool, theoretically resulting in decreased fecal sterol excretion and exacerbated dyslipidemia." (PMID 34685599, 2021).
metabolic syndrome (continued). "Besides insulin resistance and dyslipidemia, whether hyperandrogenism or dysregulations of any other hormones commonly existed in patients with PCOS might influence the serum FGF19 levels need to be further investigated." (PMID 24260557, 2013).
steatosis (23 papers, 2014 to 2025). Increased lipid within the cytoplasm of cells. "Correlation analyses within the subgroups indicated that patients with transglutaminase antibody levels ≥1 U/mL present with an invert association between FGF19 and the extent of steatosis as assessed by CAP." (PMID 35208205, 2022). "FGF19 has therefore also been suggested as a diagnostic biomarker in NASH where a decrease should indicate increases in steatosis." (PMID 33414764, 2020). "Concurrently, FGF19/21 analogs have demonstrated significant anti-steatosis, anti-inflammatory, and anti-fibrosis effects in various experimental models." (PMID 40807240, 2025). "Treatment with recombinant FGF19 was found to signicantly reduce the pathological hallmarks of NASH in the multi-tissue liver organoid-based steatosis model, such as lipid accumulation, hepatocyte damage, stiffness, and ROS production." (PMID 37497008, 2023). "Fibroblast growth factor 19 (FGF19) was repressed in CeD, while low levels were associated with steatosis, especially in patients with high levels of anti-tissue transglutaminase antibodies (anti-tTG)." (PMID 35208205, 2022). "Serum FGF19 and adiponectin-to-leptin ratio (A/L) were negatively correlated with steatosis, consistent with previous findings." (PMID 35663311, 2022). "In summary, both FGF21 and FGF19 analogues decrease steatosis, inflammation and fibrosis in various NASH models." (PMID 33414764, 2020). "The lowest median FGF19 value was in steatosis (76pg/mL; IQR 58.9–168.4) and the highest was for steatohepatitis (103.9pg/mL; IQR 70.5–187.9)." (PMID 30682184, 2019). "It has been shown that the metabolic response to FGF19 signaling in the liver is impaired in obese patients with nonalcoholic fatty liver disease (NAFLD) (steatosis) and steatohepatitis." (PMID 30134638, 2018). "This increase in FGF19/FGR4 expression in liver tissues was seen overall as a progression of steatosis to HCC." (PMID 27447573, 2016). "Intestinal activation of FXR reduces weight gain, liver glucose production and steatosis, stimulating human fibroblast growth factor-19 (FGF19)." (PMID 27657051, 2016). "In various NASH animal models, FGF-19/21 analogues decreased steatosis, inflammation, and fibrosis." (PMID 38892505, 2024). "We thus hypothesized that direct beneficial effects on steatosis of FXR activators in hepatocytes are primarily mediated through induction of hepatic FGF19 signaling." (PMID 36823355, 2023). "Multivariate regression showed that waist-to-hip ratio, fibroblast growth factor (FGF) 21, FGF19, adiponectin-to-leptin ratio, insulin, albumin, triglyceride, total-cholesterol, and alanine-aminotransferase were independent predictors of steatosis (rank-ordered by Wald)." (PMID 35663311, 2022). "The effect on steatosis is likely independent of the FGFR4/KLB complex as a FGF19 variant lacking FGFR1c/KLB activity lack metabolic activity." (PMID 33414764, 2020). "The marked net loss in liver fat by FGF19 and NGM282 is likely mediated by the FGFR1c-βKlotho and FGFR4-βKlotho receptor complexes, as an agonistic antibody against FGFR1c-βKlotho reduces steatosis and a compound upregulating CYP7A1 increases steatosis." (PMID 30679232, 2019). "FGF19 and FGF21 analogues have overlapping effect on steatosis, inflammation and fibrosis in mice and human subjects." (PMID 33414764, 2020). "Consistently, in our study, FGF19 showed negative correlation with steatosis and enhanced the predictiveness of MSI-S, demonstrating the second highest influence on FGF21." (PMID 35663311, 2022). "It is still not fully understood if a direct action on hepatocytes contribute to the positive effect of FGF19 and FGF21 on steatosis, but overexpression of an inactive KLB mutant interestingly induces intracellular lipid accumulation in HepG2 and Huh7 cells in vitro." (PMID 33414764, 2020).
steatosis (continued). "The main features of NASH pathology in metabolic models, i.e., steatosis, mild inflammation, and mild fibrosis have all been found to be improved by treatments with FGF21, as well as FGF19 and analogues thereof which may partly be driven by a decrease in BW." (PMID 33414764, 2020). "Collectively, these data show that both FGF19 and NGM282 selectively activate hepatic LXR signaling to regulate transhepatic cholesterol efflux, a key step in reverse cholesterol transport, without causing steatosis." (PMID 30679232, 2019). "Our results suggest that the FGF19 analog, NGM282, may represent an alternative strategy by coordinately enhancing HDL biogenesis and transhepatic cholesterol efflux, while ameliorating steatosis, and providing protection against the development of atherosclerotic plaques." (PMID 30679232, 2019).